SEMA3C (semaphorin 3C)
Diseases named in the same sentence as SEMA3C in open-access papers (continued):
Sharing a sentence is not in itself a finding about the gene and the disease.
autoimmune disease (1 paper, 2025). A disorder resulting from loss of function or tissue destruction of an organ or multiple organs, arising from humoral or cellular immune responses of the individual to their own tissue constituents. "One candidate, SEMA3C, a member of the semaphorin gene family, also plays significant roles in autoimmune disease, including many identified in our AD collection." (PMID 40959879, 2025).
bladder tumor (1 paper, 2024). "When we divided the patients according to the grade of bladder tumor, we observed significantly higher sema3C plasma concentrations in patients with low-grade tumors (p = 0.0132)." (PMID 39457718, 2024).
bronchopulmonary dysplasia (1 paper, 2018). Bronchopulmonary dysplasia is a chronic respiratory disease that results from complications related to lung injury during the treatment of infant acute respiratory distress syndrome in low-birth-weight premature infants or from abnormal lung development in older infants. "Interestingly, in a rat bronchopulmonary dysplasia model, Sema3C treatment reduced inflammation and apoptosis to maintain alveolar and lung vascular growth, suggesting that Sema3C may facilitate lung repair." (PMID 29642487, 2018).
Cirrhosis (1 paper, 2024). A chronic disorder of the liver in which liver tissue becomes scarred and is partially replaced by regenerative nodules and fibrotic tissue resulting in loss of liver function. "Our study found that Sema3C was upregulated in cirrhosis and HCC tissues in a DEN+CCl4-induced mouse model and highly expressed in sorafenib-resistant HCC cells." (PMID 38956074, 2024).
congenital heart disease (1 paper, 2021). A heart disease that is present at birth. "During development, semaphorin 3C downregulation in cardiac tissue is related to certain types of congenital heart disease." (PMID 34270956, 2021).
COVID-19 (1 paper, 2023). A disease caused by infection with severe acute respiratory syndrome coronavirus 2. "Furthermore, SEMA3A and SEMA3C decreased with COVID-19 severity, while SEMA3F and SEMA7A increased." (PMID 37893159, 2023). "Concentrations of the serum semaphorins SEMA3A, SEMA3C, SEMA3F, SEMA4D and SEMA7A were detectable in all patients with COVID-19." (PMID 37893159, 2023). "In conclusion, we have shown that patients with COVID-19 have different expressions of SEMA3A, SEMA3C, SEMA3F and SEMA7A than healthy controls, which correlate with disease severity and outcomes." (PMID 37893159, 2023). "In conclusion, we provide the first evidence that SEMA3A, SEMA3C, SEMA3F and SEMA7A can be considered as new biomarkers of COVID-19 severity." (PMID 37893159, 2023). "Furthermore, we showed an association of semaphorin levels with COVID-19 severity; SEMA3F and SEMA7A were higher in critical COVID-19, while SEMA3A and SEMA3C negatively correlated with COVID-19 severity and were lower in the critical group." (PMID 37893159, 2023). "While SEMA3A was decreased, SEMA3C, SEMA3F and SEMA7A were increased in COVID-19." (PMID 37893159, 2023).
Cyanosis (1 paper, 2014). Bluish discoloration of the skin and mucosa due to poor circulation or inadequate oxygenation of arterial or capillary blood. "Lastly, we addressed the question of whether cardiovascular abnormalities could be the primary cause of respiratory distress and cyanosis in KLEIP−/− mice as has been described for Foxc2- and Sema3c-deficient single-mutant mice." (PMID 24785085, 2014).
diabetes (1 paper, 2023). "Moreover, disruptions in the Sema3C-Nrp2 axis due to diabetes have been linked to corneal dysfunction, leading to issues such as delayed wound healing and impaired nerve regeneration." (PMID 37830626, 2023).
fragile X syndrome (1 paper, 2020). A genetic syndrome caused by mutations in the FMR1 gene which is responsible for the expression of the fragile X mental retardation 1 protein. "Genes which regulate axon growth and pathfinding as well as terminal branching of axons such as SEMA3C and SLITRK2 and SLITRK4 were found downregulated in iNeurons from patients with Fragile X syndrome, an ID disorder associated with epigenetic dysregulation." (PMID 32562237, 2020).
invasive breast carcinoma (1 paper, 2023). A carcinoma that infiltrates the breast parenchyma. "To define the co-expression relationship between SEMA3C and the estrogen receptor, we used mRNA expression data of SEMA3C and ESR1 from a TCGA study (Firehose Legacy-Breast Invasive Carcinoma) with 1100 samples." (PMID 37443749, 2023).
keloid (1 paper, 2022). An irregularly shaped, elevated mark on the skin caused by deposits of excessive amounts of collagen during wound healing. "The signal was further amplified when we identified dysfunctional signaling by comparing DEGs analysis between keloid and normal samples and SEMA3C was the main ligand." (PMID 36388926, 2022). "For example, we can regulate the SEMA3C pathway to observe the development of earlobe keloid formation and help us to better understand the pathogenesis of keloids." (PMID 36388926, 2022). "And interactions between SC and ECM-related subpopulations were mainly through SEMA3C signaling pathways and MK/PTN family in both earlobe keloids and chest/back keloids." (PMID 36388926, 2022).
lung adenocarcinoma (1 paper, 2015). A carcinoma that arises from the lung and is characterized by the presence of malignant glandular epithelial cells. "The expression of Sema3C was found to be upregulated in metastatic cells of lung adenocarcinoma." (PMID 26032848, 2015).
lymph node metastasis (1 paper, 2026). "Overall, we investigated the heterogeneity of TME from a single-cell perspective and demonstrated that SEMA3C serve as an effective biomarker for predicting lymph node metastasis and prognosis in PSCC." (PMID 41637545, 2026).
metabolic syndrome (1 paper, 2023). A cluster of metabolic risk factors for CARDIOVASCULAR DISEASES and TYPE 2 DIABETES MELLITUS. "Human white adipose tissue (WAT) is an important source of semaphorin 3C and greater expression is observed in the obese and metabolic syndrome, representing that semaphorin 3C plays a pathophysiological role in human WAT." (PMID 37576981, 2023).
pancreatic adenocarcinoma (1 paper, 2019). "There is considerable overlap between the effector pathways of SEMA3C and KRAS; both lead to PI3K/AKT and Raf/MEK/ERK activation and SEMA3C expression positively correlates with KRAS mutations in The Cancer Genome Atlas (TCGA) datasets of pancreatic adenocarcinoma." (PMID 30759745, 2019).
pancreatic ductal adenocarcinoma (1 paper, 2023). An infiltrating adenocarcinoma that arises from the epithelial cells of the pancreas. "To validate these clinical data in an independent cohort, we evaluated SEMA3C mRNA expression in a publicly available pancreatic ductal adenocarcinoma dataset of The Cancer Genome Atlas (TCGA-PAAD)." (PMID 37537633, 2023). "We previously identified semaphorin 3 C (SEMA3C) as a secreted protein overexpressed in pancreatic ductal adenocarcinoma (PDAC)." (PMID 37537633, 2023).
preeclampsia (1 paper, 2024). Preeclampsia is a hypertensive disorder of pregnancy that is characterized by new-onset hypertension with proteinuria presenting after 20 weeks of gestation, and depending on mild or severe forms may initially present with severe headache, visual disturbances, and hyperreflexia. "In this regard, high SEMA3C levels have been found at the maternal–fetal–placental interface during the first trimester of gestation, and SEMA3F, SEMA3B, and NRP2 are overexpressed in the placenta of women with preeclampsia." (PMID 38541683, 2024).
retinopathy of prematurity (1 paper, 2015). A bilateral retinopathy characterized by neovascularization, scarring, retinal detachment, and eventually blindness. "We have demonstrated that Sema3C is an attractive agent to specifically inhibit the formation of pre-retinal neovascular tufts in an animal model of retinopathy of prematurity." (PMID 26194913, 2015).
SARS-CoV infection (1 paper, 2023). "For example, among the mRNAs downregulated with SARS-CoV-2 infection (but not with SARS-CoV infection), SEMA3C is a theoretically calculated target of multiple upregulated tRFs and a ligand of NRP1, a SARS-CoV-2 receptor." (PMID 38203569, 2023).
ZIKV infection (1 paper, 2024). "Further, SEMA3C and SEMA3F, two members of the semaphorin class 3 family of neuronal guidance genes, were also downregulated at the 48 hpi timepoint in ZIKV infection, suggesting that ZIKV infection may reduce neuronal maturation or synapse formation." (PMID 38440980, 2024).
tumor (69 papers, 2013 to 2026). "Previous studies have found that SEMA3C is associated with tumor progression in various types of cancers, including prostate, pancreatic, brain, breast, cervical, and gastric cancers." (PMID 38321460, 2024). "SEMA3C levels positively correlated with tumor volume (p = 0.0003), and High SEMA3C levels were also associated with invasive features, such as lymphatic and neural invasion, compared with that in Low SEMA3C levels in primary PDAC." (PMID 37537633, 2023). "Our study provides further support for this association, as we found that SEMA3C activates these pathways and drives tumor progression in tamoxifen-resistant cells." (PMID 37443749, 2023). "The expression of Ki67 is strongly associated with tumor cell proliferation and growth and our IHC results show that the level of Ki67 is much higher in the vehicle group than that in the SEMA3C inhibitor group." (PMID 35785187, 2022). "Higher expression of SEMA3C in hepatocellular carcinoma is associated with larger tumor size and lower survival." (PMID 30759745, 2019). "Among semaphorins, SEMA3C has been found to be associated with tumor progression and prognosis across multiple tumor types." (PMID 31649890, 2019). "Among other class 3 semaphorins, SEMA3C has been found to be associated with tumor progression and poor prognosis across multiple tumor types, including pancreatic, gastric, prostate, and breast cancer, as well as glioma." (PMID 31649890, 2019). "PlexinD1 is also expressed in tumor-associated blood vessels, and it is possible that secretion of Sema3C from GSCs in the perivascular niche can recruit and communicate with endothelial cells." (PMID 29642487, 2018). "There are some studies in which Sema3C is associated with GBM tumor progression." (PMID 31726800, 2019). "To determine whether SEMA3C can drive activation of EGFR and MET signaling in other cell types, we first screened cBioPortal for Cancer Genomics data for tumor types that showed an association of high SEMA3C expression and poor prognosis." (PMID 29348142, 2018). "It is also worth noting that SEMA3C is associated with tumor cell motility and may therefore contribute to cancer cell dissemination." (PMID 28038451, 2017). "Interestingly, SEMA3C knockdown also could control the ERK signaling pathway, which led us to inquire whether SEMA3C could mediate or be involved in the regulation of PD-L1 expression in tumor and tumor associated macrophages (TAMs)." (PMID 35785187, 2022). "Mechanistically, the expression of arachidonate 12-lipoxygenase (ALOX12) in HEVs is promoted by tumour-derived semaphorin 3 C (SEMA3C)." (PMID 42115618, 2026). "In contrast, SEMA3C is upregulated in cancers like prostate cancer and promotes tumor progression via EGFR, HER2, and MET activation through Plexin B1." (PMID 41009819, 2025). "Therapeutic strategies that restore SEMA3A/3F signaling or inhibit SEMA3C, such as semaphorin analogs, Plexin B1-Fc decoys, and anti-SEMA3C antibodies, have shown promise in reducing tumor growth and neural infiltration in preclinical cancer models." (PMID 41009819, 2025). "Overexpression of SEMA3C was identified to promote proliferation, migration, and invasion of tumor cells; thus, it will provide a potential biomarker for diagnosis, prognosis, and personalized medicine in TSCC." (PMID 39941210, 2025). "In vivo experiments showed that knockdown of SEMA3C attenuates tumor growth, and overexpression of SEMA3C increases tumor size and weight." (PMID 38321460, 2024). "In vitro results indicated an important role of SEMA3C in promoting tumor progression by enhancing the capacities of proliferation, migration, and invasion." (PMID 38321460, 2024). "Hep3B cells overexpressing Sema3C showed a significantly higher tumor-initiating capacity compared to control cells." (PMID 38956074, 2024). "The combination treatment effectively inhibited tumor growth, suggesting that Sema3C suppression sensitizes HCC to sorafenib." (PMID 38956074, 2024).
tumor (continued). "Given that CSCs contribute to tumor recurrence, the impact of Sema3C on HCC relapse was examined using the GSE14520 dataset." (PMID 38956074, 2024). "This signalling pathway consisted of three secreted proteins (SEMA3A, SEMA3B and SEMA3C), which were correlated with tumour metastasis and unfavourable therapy response." (PMID 39187937, 2024). "Our findings demonstrate for the first time that Sema3C reshapes the tumor stroma to maintain tumor stemness." (PMID 38956074, 2024). "The results indicated that Sema3C was predominantly expressed in tumor cells and, to a lesser extent, in stromal cells, while it was rarely expressed in normal hepatocytes or endothelial cells, consistent with our in vitro cell line results." (PMID 38956074, 2024). "Less is known about the immunoregulatory role of SEMA3C, but it was shown that SEMA3C regulates fibrosis, vascular development, pathological angiogenesis and the migration of tumor cells." (PMID 37893159, 2023). "Combination therapy with SEMA3C knockdown and GnP reduced tumor growth and peritoneal dissemination." (PMID 37537633, 2023). "Specifically, the tumor reduction effect of the combination of GnP and SEMA3C knockdown was evaluated by measuring the change in tumor volume using the mean tumor volume of each untreated group as the baseline." (PMID 37537633, 2023). "As a secreted protein, Sema3C facilitates communication between neighboring GSCs to promote tumor progression, thereby expanding their population and reinforcing their malignant phenotype collectively." (PMID 37080989, 2023). "We also found the relevance of SEMA3C expression levels and functions in phenotypes such as cell invasion, CSC properties, drug resistance, and tumor growth in the SEMA3C knockdown cells and overexpressing cells." (PMID 37537633, 2023). "In our preclinical study, SEMA3C knockdown enhanced the efficacy of GnP in reducing tumor growth and peritoneal carcinomatosis." (PMID 37537633, 2023). "For example, several SEMA3s (e.g. SEMA3A and SEMA3B) act as inhibitors of tumor progression, whereas SEMA3C exhibits both anti- and pro- tumorigenic effects." (PMID 36942388, 2023). "In two different models, knockdown of either Sema3C or TCF1 alone reduced tumor growth and extended animal survival compared to control animals." (PMID 37080989, 2023). "Sema3C has a role in promoting tumor development, and it is hypomethylated, and its expression increases with tumor progression in PC." (PMID 36713527, 2022). "Together, these results indicated that the tumorigenesis of the KPC tumor bearing mice was inhibited by SEMA3C inhibition." (PMID 35785187, 2022). "Taken together, our data suggest that SEMA3C plays a substantial role in promoting cancer cell survival by regulating the autophagy process and impacting the tumor environment immune response." (PMID 35785187, 2022). "H&E results showed that the tumor was dense in the vehicle group while there were fewer tumor cells and more stroma in the group treated with the SEMA3C inhibitor." (PMID 35785187, 2022). "Semaphorin 3C (Sema3C) and semaphorin 3D (Sema3D) play an important role in tumor development by regulating cell proliferation, migration, invasion, and angiogenesis processes." (PMID 35350431, 2022). "We further demonstrated the dramatic autophagy inhibition response by exploring the autophagy-related proteins and significant decrease in PD-L1 level in tumor tissue with treatment of SEMA3C inhibitor." (PMID 35785187, 2022). "Actually, Sema3C is a secreted semaphorin with a pleiotropic and partly controversial activity in the tumor microenvironment, as it was reported to variedly regulate epithelial-to-mesenchymal transition, cell migration angiogenesis, and cancer cell stemness." (PMID 33537086, 2021). "Angiogenesis can also be increased in the presence of semaphorins, and receptors for semaphorin 3C, particularly plexin D1, are upregulated in the tumor vasculature making it a potential drug candidate." (PMID 34270956, 2021).